SASH1 (SAM and SH3 domain containing 1)
Diseases named in the same sentence as SASH1 in open-access papers (continued):
Sharing a sentence is not in itself a finding about the gene and the disease.
dyschromatosis (7 papers, 2017 to 2025). "Other than the peculiar type of dyschromatosis, the SASH1 mutations are also associated with another phenotype of skin pigmentation disorder: multiple lentigines." (PMID 40115815, 2025). "Overall, we reported a phenotype of dyschromatosis with SASH1 mutations in a five-generation Chinese family and a sporadic case and examined the clinicopathologic features of this peculiar dyschromatosis." (PMID 40115815, 2025). "Several heterozygous missense mutations in SASH1 have been identified in patients with dyschromatosis." (PMID 40584949, 2025). "A peculiar phenotype of dyschromatosis presented as multiple lentigines and hypopigmentation with various sizes and shapes was found to be associated with SASH1 mutations and has recently been reported frequently." (PMID 40115815, 2025). "In this study, the clinicopathologic features of the dyschromatosis caused by SASH1 mutations are analyzed to gain a better understanding of this disorder and make a clearer classification of dyschromatosis without systemic involvement." (PMID 40115815, 2025). "This research also presents a case study of a sporadic patient with dyschromatosis caused by SASH1 mutations and shows different clinicopathological characteristics form DSH, DUH and FPHH." (PMID 40115815, 2025). "It has been demonstrated that the missense mutation of SASH1 has been shown to be correlated with genodermatosis, such as dyschromatosis universalis hereditarian." (PMID 37322027, 2023). "So far, totally 11 heterozygous missense mutations in SASH1 have been identified in patients with dyschromatosis, in which seven mutations contribute to DUH phenotype and four mutations lead to multiple lentiginous." (PMID 32849825, 2020). "High consistency in clinicopathological features and genetic basis in these two SASH1-related pigmentary disorders suggests that SASH1 mutations cause multiple lentigines and dyschromatosis which might belong to a disease spectrum." (PMID 40115815, 2025). "In the form of dyschromatosis related to SASH1 mutations, the lentigo-like macules and hypopigmented macules or patches started on the face or on the dorsa of interphalangeal and metacarpophalangeal joints of hands in infancy or early childhood and extended progressively onto the body with age." (PMID 40115815, 2025). "The dyschromatosis caused by SASH1 mutations is sometimes considered to be a subtype of DUH." (PMID 40115815, 2025). "The most prominent feature of SASH1-related dyschromatosis is multiple lentigo-like macules coexisting with variable and symmetrical hypopigmentation which was prominent on the joint protuberances." (PMID 40115815, 2025). "Our findings not only help enhance a more comprehensive understanding of SASH1-related dyschromatosis but also provide a useful hint for the diagnosis of pigmentary dermatosis." (PMID 40115815, 2025). "A majority of SASH1-related dyschromatosis was reported as a subtype of DUH." (PMID 40115815, 2025). "Recently, several studies have documented a distinct group of dyschromatosis in an autosomal dominant inherence pattern caused by mutations of SAM (sterile alpha motif) and SH3 (Src homology domain 3) domain-containing protein 1 gene (SASH1)." (PMID 40115815, 2025). "However, the SASH1-related dyschromatosis presented as a distinct clinical phenotype different from that in patients with DUH." (PMID 40115815, 2025). "Also, the mitochondrial abnormalities within melanocytes were another pathological feature of SASH1-related dyschromatosis." (PMID 40115815, 2025).
dyschromatosis (continued). "Alteration in melanocytes’ number participated in the SASH1-related dyschromatosis and the distribution pattern of melanosomes within keratinocytes is consistent with the previously reported distribution of melanosomes in keratinocytes from different skin types." (PMID 40115815, 2025). "The pathological results also indicated that SASH1-related dyschromatosis and DUH may be different entities." (PMID 40115815, 2025). "Additionally, the high consistency in clinical manifestation, pathological expression, and genetic basis between the SASH1-related dyschromatosis and SASH1-related multiple lentigines suggests that these two conditions might be different phenotypes of a disease spectrum." (PMID 40115815, 2025). "Though, the multiple lentigo-like macules and the symmetrical hypopigmented patches, especially on the joint prominences, are the clinical characteristics of SASH1-related dyschromatosis but they are not commonly seen in patients with DUH." (PMID 40115815, 2025). "The clinical phenotypic, pathologic, and genetic differences between SASH1-related dyschromatosis and other dyschromatosis of autosomal dominant inheritance including DUH, DSH, or FPHH suggest that the SASH1-related dyschromatosis might be a distinct entity." (PMID 40115815, 2025). "To elucidate whether SASH1-related dyschromatosis is a subtype of DUH, we analyzed the pathological manifestations of SASH1-related dyschromatosis." (PMID 40115815, 2025). "However, the objective of the present study is to focus on the clinical manifestation and genetic basis behind SASH1-related dyschromatosis despite the lack of adequate pathological analysis." (PMID 40115815, 2025). "Therefore, the clinicopathological features do not support the idea that DUH and SASH1-related dyschromatosis are identical entities." (PMID 40115815, 2025).
glioma (6 papers, 2015 to 2022). A benign or malignant brain and spinal cord tumor that arises from glial cells (astrocytes, oligodendrocytes, ependymal cells). "Furthermore, higher SASH1 expression was associated with better postoperative survival in patients with glioma." (PMID 26424902, 2015). "Similarly, sex and glioma grades and SASH1 expression were significantly associated with survival status that employed the Cox regression model." (PMID 26424902, 2015). "Research shows that circ-ITCH exerts a tumor-suppressive function upon glioma cells through the miR-106a-5p/SASH1 axis and miR-214/ITCH-Wnt/β-catenin pathway." (PMID 35327551, 2022). "Previously, it was found that SASH1 showed lower expression levels in high-grade glioma tissue samples in comparison with low-grade samples Reduced expression of SASH1 has been correlated to poor prognosis." (PMID 32746854, 2020). "However, what causes the downregulation of SASH1 gene expression in glioma is unknown." (PMID 31138780, 2019). "For this purpose, we developed SASH1 siRNA and an Adv4-SASH1 virus as tools to deplete or replenish SASH1 expression, respectively, in cultured astrocytes or in C6 glioma cells." (PMID 31138780, 2019). "Our previous studies found that SASH1 expression in high-grade gliomas was significantly lower than that in low-grade gliomas and that low SASH1 expression was also correlated with poor prognosis." (PMID 31138780, 2019). "We also verified in the present study that HMGB1, a protein present in large amounts in glioma cell nuclei, contributed to SASH1 gene methylation, thereby resulting in downregulated SASH1 expression." (PMID 31138780, 2019). "According to Kaplan-Meier analysis, there was a significant positive correlation between SASH1 expression and postoperative survival in patients with glioma (P < 0.05)." (PMID 26424902, 2015). "SASH1 expression strongly correlated with glioma grades, showing higher expression at a lower grade, which decreased significantly as grade increased." (PMID 26424902, 2015). "SASH1 expression was significantly correlated with glioma grade, showing decreased expression at more advanced stages." (PMID 26424902, 2015). "According to the results of this regression analysis, low expression of SASH1 is an independent prognostic factor for shorter survival in patients with glioma." (PMID 26424902, 2015). "We investigated SASH1 expression in glioma cases to determine its clinical significance on glioma pathogenesis and prognosis." (PMID 26424902, 2015). "Similarly, circ-ITCH was demonstrated to stimulate SASH1 levels by sponging miR-106a-5p to affect glioma cell proliferation and invasion." (PMID 35327551, 2022). "Accumulating evidence indicates that SASH1 may be a tumor suppressor gene and that its expression is either decreased or lost in most cancers, including human glioma." (PMID 31138780, 2019). "However, the functions of SASH1 in normal astrocytes and the reasons for the reductions in SASH1 levels in glioma tissues are unclear." (PMID 31138780, 2019). "The results revealed that more HMGB1 protein occupies the CpG sites of the SASH1 gene in C6 glioma cells than in astrocytes and that this increased occupation may contribute to the methylation of these sites in C6 cells." (PMID 31138780, 2019). "Therefore, SASH1 gene promoter methylation contributes to the downregulated SASH1 expression in glioma." (PMID 31138780, 2019). "SASH1 protein expression was almost 2.5-fold higher in astrocytes than in C6 glioma cells." (PMID 31138780, 2019). "The SASH1 expression level could be effectively manipulated in C6 glioma cells or astrocytes by Adv4-SASH1 application or SASH1 siRNA treatment, respectively." (PMID 31138780, 2019). "Therefore, in this study, we manipulated SASH1 gene expression using siRNA in cultured astrocytes and compared these cells to C6 glioma cells transfected with Adv4-SASH1." (PMID 31138780, 2019).
glioma (continued). "Similar to these previously published observations our results suggest a putative role for SASH1 in the genesis of glioma and may indicate that SASH1 gene deletions might occur to varying degrees during tumor progression." (PMID 26424902, 2015). "Furthermore, SASH1 expression was positively correlated with better postoperative survival in patients with glioma." (PMID 26424902, 2015). "In glioma tissues, as tumor grade increased, SASH1 expression decreased or was completely absent." (PMID 26424902, 2015). "We previously studied the impact of SASH1 on the biological behavior of glioma cells and found that after overexpressing SASH1 plasmid U251 glioma cells exhibited significantly reduced cell viability, proliferation, and invasion and a significantly higher apoptotic index." (PMID 26424902, 2015). "However, the specific mechanism of how SASH1 affects the biological behavior of a tumor is unclear, and the impact of SASH1 expression on glioma is yet to be determined." (PMID 26424902, 2015). "We then suggested SASH1 gene may play a tumor inhibitory role in glioma cells." (PMID 26424902, 2015). "Therefore, we hypothesize that SASH1 expression level could be closely and negatively correlated with glioma grade." (PMID 26424902, 2015). "Similar studies have also demonstrated the difference between the protein patterns of normal and glioma cells and the opposite effect of extracellular high-mobility group protein 1 (HMGB1) and astrocytic HMGB1 on SASH1 gene expression in one glioma cell line." (PMID 33178687, 2020). "Of the 121 cases of glioma, 66.9% (81 cases) had low SASH1 expression and these were mostly grade III-IV cases (26 + 40), whereas 33.1% (40 cases) had high SASH1 expression and these were mostly grades I-II (4 + 19)." (PMID 26424902, 2015). "Our previous clinical investigation found that SASH1 was widely expressed in normal brain tissues but reduced or absent in glioma tissues." (PMID 31138780, 2019). "Statistical analysis revealed that SASH1 expression was not correlated with age or sex (P > 0.05) but that SASH1 expression was significantly correlated with glioma grade, with higher expression at lower grades, and vice versa (P < 0.01)." (PMID 26424902, 2015). "The differences in SASH1 expression levels between nontumor tissues, low-grade glioma, and high-grade glioma were all statistically significant." (PMID 26424902, 2015). "In the present study, immunohistochemical and western blot analyses of SASH1 protein expression revealed that SASH1 expression was much higher in nontumorous tissues compared with glioma tissues, and that expression was closely correlated with glioma grade." (PMID 26424902, 2015). "To investigate the expression of SASH1 protein in glioma and nontumorous tissue, we performed IHC analysis on primary patient-derived tissues." (PMID 26424902, 2015). "Western blotting revealed that SASH1 expression in glioma tissues was significantly lower than that in nontumor tissues." (PMID 26424902, 2015). "Another study showed that a tumor suppressor, SAM, and SH3 domain-containing protein 1 (SASH1), was dysregulated or absent in glioma cells." (PMID 33178687, 2020).
dyschromatosis universalis hereditaria (4 papers, 2017 to 2025). A pigmentation disease characterized by reticulate hyper- and hypo-pigmentated macules in a generalized distribution. "When identifying the causative gene of dyschromatosis universalis hereditaria (DUH), we found three mutations encoding amino acid substitutions in the gene SAM and SH3 domain containing 1 (SASH1), and SASH1 was associated with guanine nucleotide‐binding protein subunit‐alpha isoforms short (Gαs)." (PMID 27885802, 2017).
hepatocellular carcinoma (4 papers, 2020 to 2024). A malignant tumor that arises from hepatocytes. "Overexpression of SASH1 in hepatocellular carcinoma cells was found to inhibit SHH, SMO, PTC, and GLI1 expression, thereby reducing proliferation, migration/invasion, and EMT progression." (PMID 38498906, 2024). "SAM- and SH3-domain containing 1 (SASH1) inhibit hepatocellular carcinoma invasion and migration by inactivating the HH and PI3K/AKT pathways in vitro and in vivo." (PMID 35433472, 2022).
melanoma (3 papers, 2016 to 2025). A malignant, usually aggressive tumor composed of atypical, neoplastic melanocytes. "Remarkably, another cancer-related mutation in EphA8-Sam (i.e., the melanoma-linked R942H substitution) also blocks the interaction with SASH1-Sam1 by possibly avoiding the formation of crucial contacts with D656 from SASH1-Sam1." (PMID 39942820, 2025). "Western blotting demonstrated that SASH1 mutations significantly increased TYRP1, Rab 27a, Pmel17 and tyrosinase protein levels in SK‐MEL‐28 cells, a pigmented melanoma cell line and NHEMs." (PMID 27885802, 2017).
non-small cell lung carcinoma (3 papers, 2020 to 2023). A group of at least three distinct histological types of lung cancer, including non-small cell squamous cell carcinoma, adenocarcinoma, and large cell carcinoma. "As these cellular processes are frequently disrupted in human tumours and little is known about the role of SASH1 in the pathogenesis of the disease, we analysed the prognostic value of SASH1 in non-small cell lung cancers using publicly available datasets." (PMID 33122723, 2020). "Our ranking of nodes with importance based on the betweenness centrality revealed that the most important node for LUSC was Cg08133058, corresponding to the gene SASH1, which is a prognostic indicator and a potential therapeutic target in non-small-cell lung cancer." (PMID 36676027, 2022).
preeclampsia (3 papers, 2020 to 2023). Preeclampsia is a hypertensive disorder of pregnancy that is characterized by new-onset hypertension with proteinuria presenting after 20 weeks of gestation, and depending on mild or severe forms may initially present with severe headache, visual disturbances, and hyperreflexia. "But it is uncertain whether the upregulation of SASH1 in the placenta is the cause of trophoblast insufficient invasion resulting in preeclampsia or a consequence of changes in the uteroplacental microenvironment." (PMID 33134379, 2020). "The expression of SASH1 was significantly increased in patients with preeclampsia both in the predicted and qPCR experiment results." (PMID 37389124, 2023). "Previous studies using RNA sequencing have found that SASH1 is upregulated in the placenta of patients with preeclampsia, indicating that SASH1 plays a vital role in this organ during preeclampsia." (PMID 37389124, 2023). "In our study, SASH1 was screened as a characteristic gene of preeclampsia, and its expression in the placenta of patients with preeclampsia was higher." (PMID 37389124, 2023). "Characteristic genes, LEP, SASH1, RAB6C, and FLT1 can be used as diagnostic and therapeutic targets for preeclampsia, and they are associated with immune cell infiltration." (PMID 37389124, 2023). "In the present study, we screened LEP, FLT1, RAB6C, and SASH1 as potential biomarkers for preeclampsia." (PMID 37389124, 2023). "Our findings suggest that LEP, SASH1, RAB6C, and FLT1 can be used as placental markers for preeclampsia and they are associated with various immune cells." (PMID 37389124, 2023). "The expression of SASH1 was significantly increased in the placenta of patients with preeclampsia but decreased in the blood." (PMID 37389124, 2023). "The results of this study were consistent with this RNA sequencing data that the expression of SASH1 protein was significantly higher in the placenta of preeclampsia than that of the normotensive control pregnancies." (PMID 33134379, 2020). "The present study reveals that SASH1 is significantly upregulated in the placenta of preeclampsia and overexpression of SASH1 can significantly suppress the proliferation, migration, and invasion but induce apoptosis of trophoblast cells in vitro." (PMID 33134379, 2020). "SASH1 is significantly upregulated in the placenta of preeclampsia, and overexpression of SASH1 can inhibit the proliferation, migration, and invasion, but induce apoptosis of trophoblast cells in vitro." (PMID 33134379, 2020). "SASH1 mRNA has been found upregulated in the placenta of preeclampsia by RNA sequencing compared to that of healthy pregnancy." (PMID 33134379, 2020). "The correlation between SASH1 and trophoblast functions was discussed to provide a new therapeutic target for treating preeclampsia." (PMID 33134379, 2020). "Higher expression of SASH1 was detected in placental tissues collected from patients with preeclampsia, compared with those from gestational age-matched control samples." (PMID 33134379, 2020). "Furthermore, the SASH1 levels in the placenta of patients with preeclampsia were significantly upregulated (p = 0.028)." (PMID 37389124, 2023). "Another study showed that SASH1 was significantly upregulated in placentas with preeclampsia." (PMID 37389124, 2023). "In summary, LEP, FLT1, RAB6C, and SASH1 were identified as potential biomarkers of preeclampsia." (PMID 37389124, 2023). "Flow cytometry analysis exhibited that SASH1 overexpression could significantly increase trophoblast cell apoptosis, suggesting that SASH1 may induce preeclampsia by promoting apoptosis of trophoblast." (PMID 33134379, 2020). "Interestingly, RNA sequencing revealed that SASH1 was upregulated in the placenta of preeclampsia patients, implicating its function in preeclampsia." (PMID 33134379, 2020). "However, SASH1 showed a downward trend in the blood samples of patients with preeclampsia." (PMID 37389124, 2023).